HAUS7 (HAUS augmin like complex subunit 7)
Description:
Contributes to mitotic spindle assembly, maintenance of centrosome integrity and completion of cytokinesis as part of the HAUS augmin-like complex.
Synonyms: UCHL5IP; UIP1
Tractability: Antibody: its Gene Ontology location is reachable by antibodies, with high confidence. PROTAC: ubiquitination databases record sites on it; its protein half-life has been measured.
Gene: Protein-coding gene on chromosome X (153,447,655 to 153,495,516, reverse strand). Ensembl gene ENSG00000213397.
Subcellular location: Cytoplasm, cytoskeleton, microtubule organizing center, centrosome; Cytoplasm, cytoskeleton, spindle
Subcellular location (Human Protein Atlas): Centrosome; Plasma membrane; Basal body; Mid piece; Nucleoli; Principal piece
Pathways (Reactome):
Cell Cycle: AURKA Activation by TPX2; Loss of Nlp from mitotic centrosomes; Loss of proteins required for interphase microtubule organization from the centrosome; Recruitment of NuMA to mitotic centrosomes; Recruitment of mitotic centrosome proteins and complexes; Regulation of PLK1 Activity at G2/M Transition
Organelle biogenesis and maintenance: Anchoring of the basal body to the plasma membrane
Gene Ontology:
Molecular function: protein binding; thioesterase binding
Biological process: centrosome cycle; spindle assembly; microtubule organizing center organization; regulation of microtubule nucleation
Cellular component: centrosome; HAUS complex; mitotic spindle microtubule; cytosol; spindle
Homologues: Orthologues: chimpanzee HAUS7 (99% identical), macaque HAUS7 (89% identical), dog HAUS7 (70% identical), pig HAUS7 (69% identical), guinea pig HAUS7 (65% identical), mouse Haus7 (65% identical), rat Haus7 (65% identical), zebrafish haus7 (31% identical).
Diseases named in the same sentence as HAUS7 in open-access papers:
HAUS7 is named in the same sentence as 5 diseases in open-access papers, as found by Europe PMC text mining. Sharing a sentence is not in itself a finding about the gene and the disease. The quoted sentences say what the papers report.
glioma (1 paper, 2023). A benign or malignant brain and spinal cord tumor that arises from glial cells (astrocytes, oligodendrocytes, ependymal cells). "Low expression of HAUS4 and HAUS6 and high expression of HAUS1, HAUS3, HAUS5, HAUS7, HAUS8 may be risk factors for poor prognosis in glioma patients." (PMID 37161065, 2023). "The research found that expression levels of the Augmin family genes HAUS1, HAUS3, HAUS4, HAUS5, HAUS6, HAUS7, and HAUS8 was all related with survival rates of glioma patients." (PMID 37161065, 2023).
HAUS7 also shares sentences with these, for which no sentence is quoted: breast carcinoma (1 paper); Obesity (1); tumor (1); type 2 diabetes (1).